DKK3 (dickkopf Wnt signaling pathway inhibitor 3)
Diseases named in the same sentence as DKK3 in open-access papers (continued):
Sharing a sentence is not in itself a finding about the gene and the disease.
cancer (123 papers, 2004 to 2026). A tumor composed of atypical neoplastic, often pleomorphic cells that invade other tissues. "Next, we aimed to dissect the molecular alterations mediating the tumorigenic effects of DKK3 loss at end‐stage cancers." (PMID 41147409, 2026). "During the progression of mouse and human PDAC, DKK3 expression shifted from epithelial dysplastic cells to cancer‐associated fibroblasts (CAFs)." (PMID 41147409, 2026). "The direct effect is caused by REIC/Dkk-3-mediated endoplasmic reticulum (ER) stress via an apoptosis signal-regulating kinase 1 (ASK1)-c-jun N terminal kinase (JNK) pathway in the infected cancer cells." (PMID 36869893, 2023). "DKK-3 has a dual role in cancer, making its use as a diagnostic/prognostic biomarker and/or as a therapeutic target complex and context-dependent." (PMID 38201279, 2023). "DKK-3 expression has been found to be high in cancer-associated fibroblasts (CAFs) of the stroma of colon, ovarian and estrogen receptor-negative breast cancers and to be associated with worse prognosis." (PMID 38201279, 2023). "Even though future studies need to elucidate DKK3 or partner and the associated signaling pathway, our data to some degree represents a viable drug candidate for the development of novel anti-cancer therapies." (PMID 35924156, 2022). "Dkk-3 levels in blood and urine have been observed in non-cancer settings, in particular, Dkk-3 plasma levels are associated with cardiovascular risk factors including age, male sex, body mass index, and glucose levels." (PMID 36497305, 2022). "Meanwhile, in many types of cancers, the failure of its normal expression is closely associated with CpG island methylation on the DKK3 promoter." (PMID 35303365, 2022). "Taken together, these findings suggest that aberrant reduction in DKK3 expression is a clinical biomarker for identifying high-risk cancer patients with poor prognoses." (PMID 35205672, 2022). "Nevertheless, DKK-3 downregulation has been correlated with β-catenin accumulation in several cancers; however, the underlying molecular mechanisms remain to be fully understood." (PMID 34451907, 2021). "Stromal expression of other DKK genes across various cancer types was less consistent, suggesting that DKK3 is the only DKK factor commonly associated with cancer stroma." (PMID 30631061, 2019). "Loss of Dkk-3 expression is particularly observed in some types of cancer and, in in vitro studies was revealed that the impact of Dkk-3 on tumor growth is mediated by regulation of apoptosis." (PMID 30680070, 2018). "Loss of Dkk3 expression in cancer is associated with hyperproliferation and dysregulated ß-catenin signaling, and ectopic expression of Dkk3 halts cancer growth." (PMID 28738084, 2017). "Although DKK3 has previously been shown to influence migratory and invasive phenotypes in multiple cancer cell types, an association of cell surface modifications that can impact cell mobility has not been shown." (PMID 28249601, 2017). "In this study, we show that the Dkk3 gene encodes a second vital intracellular isoform, DKK3b, that inhibits hyperproliferation in cancer cells by blocking the ß-catenin nuclear translocation downstream of the Wnt-regulated ß-catenin destruction complex." (PMID 28738084, 2017). "Loss of DKK3 has already been shown to be a consistent and widespread alteration among various human cancer types." (PMID 27467270, 2016). "Various studies have shown that REIC/DKK-3 downregulation is closely associated with the pathological malignancy of clinical specimens of various cancer types." (PMID 26658102, 2016). "Loss of DKK3 expression served as a prognostic factor for unfavorable outcome in carcinomas of all subtypes except for HER2-postive cases." (PMID 27467270, 2016). "Although DKK3 has been mainly associated with cancer, it is found that recombinant DKK3 protein induces human monocyte differentiation to immature dendritic cells." (PMID 26105053, 2015).
cancer (continued). "The induction of apoptosis in cancer cells is mainly caused by endoplasmic reticulum (ER) stress induced by the overproduction of REIC/Dkk-3 in the cells." (PMID 24498395, 2014). "The identification of TME modulations, marked by an abundance of myCAFs, indicates that DKK3 loss‐of‐function in cancer cells may also impact the stromal immune landscape." (PMID 41147409, 2026). "In this context, we attempted to identify HNSCC-specific cancer-associated genes focusing on DKK3." (PMID 36376957, 2022). "Downregulation of REIC/Dkk-3 is associated with the malignancy of various cancer types." (PMID 28599655, 2017). "Thus, the interaction of REIC/DKK-3 with SGTA and TCTEX-1 is implicated in cancer-related signaling suppressed by the tumor suppressor REIC/DKK-3." (PMID 26658102, 2016). "Compared to the expression in normal breast tissue samples, TNBC cases revealed a significantly reduced DKK3 expression (median fold change (FC): 12.7, P < 0.001), while expression loss was less abundant in carcinomas of the HER2-positive (median FC: 3.9) and luminal subtype (median FC: 2)." (PMID 27467270, 2016). "Overall, our studies provide evidences that DKK3 is contributing to the immune-suppressive function of MSCs and may explain the underlying mechanism in those cancer types that show better prognosis associated with impaired DKK3 expression." (PMID 26734010, 2015). "Recent in vivo experiments support a hypothesis that the loss of DKK3 expression promotes an aggressive cancer phenotype." (PMID 18826564, 2008). "Prostate glands of Dkk3 mutant mice exhibit changes in prostate tissue organization and increased prostate epithelial cell proliferation, suggesting that Dkk-3 is required to maintain a normal microenvironment and that its loss could play a role in cancer progression." (PMID 29858602, 2018). "Strikingly, Dkk3‐null cancer cells led to an increase in myCAF gene expression (ACTA2, CTGF, PDGFRB), with concomitant downregulation of inflammatory CAF markers (CXCL12, CXCL2) in PSCs." (PMID 41147409, 2026). "DKK3 expression evolves during progression and drives cancer severity by orchestrating cellular and molecular signaling pathways." (PMID 41147409, 2026). "DKK3 expression is notably found in CAFs within human PDAC single‐cell datasets but is lost or downregulated in the carcinomas of PDAC patients." (PMID 41147409, 2026). "Many reports have shown decreased expression of DKK3 in cancers, largely due to promoter hypermethylation." (PMID 40917921, 2025). "We previously attempted to seek specific cancer-associated genes in HNSCC/OSCC and focused on DKK3 as a candidate." (PMID 40917921, 2025). "To assess a human gene other than the GFP reporter, we selected the REIC/DKK-3 (REIC) gene for insertion into pSAKA-4B based on our extensive research on this gene in cancer biology." (PMID 39570532, 2024). "DKK3 is omnipresent in normal human tissues, including the brain; however, it is significantly depleted in various cancer cell types." (PMID 38993819, 2024). "While DKK3 expression is downregulated in the majority of cancers, also upregulation of DKK3 has been observed in some types of cancer." (PMID 35796776, 2023). "Altogether, these results indicate that ΔNp63 regulates cancer cell phagocytosis by macrophages through DKK3 expression and secretion." (PMID 38022675, 2023). "We have been investigating the protein nature of REIC/Dkk-3 and its usefulness in clinical applications for cancer patients." (PMID 36869893, 2023). "In contrast to the potential benefits of REIC/Dkk-3, we need to consider the shortcomings of the use of this protein for cancer treatment." (PMID 36869893, 2023). "DKK-3 expression has been shown to increase cancer cell apoptosis, in a phosphorylated JNK-dependent manner, via endoplasmic reticulum (ER) stress signaling." (PMID 38201279, 2023). "Such amelioration engineering of REIC/Dkk-3 will help improve the future applications of Ad-REIC cancer gene therapy." (PMID 36869893, 2023).
cancer (continued). "For instance, ectopic overexpression of DKK-3 has been shown to decrease cancer cell proliferation in vitro through the inhibition of the Wnt/β-catenin pathway." (PMID 38201279, 2023). "Attempts have been made to express DKK-3 with an adenoviral vector (Ad-REIC) in cancer patients with low levels of DKK-3." (PMID 38201279, 2023). "The adenovirus-REIC/Dkk-3 expression vector (Ad-REIC) has been the focus of numerous clinical studies due to its potential for the quenching of cancers." (PMID 36869893, 2023). "Epigenetic modifications, such as chromatin condensation and promoter methylation, are both the mechanisms of DKK3 silencing in the majority of other cancers." (PMID 38269250, 2023). "DKK-3 in CAFs impacts their extracellular matrix-remodeling abilities, with consequences on matrix stiffness and cancer invasion properties." (PMID 38201279, 2023). "In conclusion, DKK-3 appears to have a dual role, acting either to promote or repress cancer depending on the specific tissue and/or cell context." (PMID 38201279, 2023). "Single-cell RNA-seq analysis of human BCs revealed that Dkk3 is expressed by multiple cells within the breast microenvironment, including both normal and cancer epithelial cells such as TNBC cells." (PMID 37847565, 2023). "We herein report a novel function of the extracellular REIC/Dkk-3—namely, regulation of an immune checkpoint via modulation of PD-L1 on the cancer-cell surface." (PMID 36869893, 2023). "Currently, the role of DKK3 in cancer is poorly understood, with both inhibitory and beneficial functions being reported in tumors." (PMID 37847565, 2023). "Most importantly, our data provides evidence that ΔNp63 in cancer cells induces the expression of diffusible immunomodulators by cancer cells, including Dickkopf-related protein 3 (DKK3), that activates the NF-κB signalling pathway in immune cells." (PMID 38022675, 2023). "It has been documented that DKK3 is abnormally expressed in numerous kinds of cancer and can suppress cancer cell migration, invasion, and proliferation through multiple pathways." (PMID 35303365, 2022). "We observed endocytosis of secreted DKK3 6 h after treatment, which showed anti-proliferative activity, as endogenous DKK3 is downregulated in cancer cells and lost in paclitaxel-resistant cells." (PMID 35205672, 2022). "A wealth of data from in vitro and xenograft cell models in multiple cancer types have correlated changes in DKK3 expression with disease progression." (PMID 36497305, 2022). "Although Dkk-3 inhibits cancer cell proliferation, its function in stromal cells, particularly in a cancer setting, is less clear." (PMID 36497305, 2022). "DKK3 knockdown attenuated ESCC-derived cancer cell proliferation and significantly suppressed the ESCC-derived cell growth in vivo." (PMID 36376957, 2022). "Navitoclax (ABT-263) reduced the growth of cancer cell lines with high DKK3 expression (r = −0.338, p = 0.018 [Pearson’s correlation] and 0.023 [Student’s t test])." (PMID 35599254, 2022). "At both mRNA and protein levels, Dkk3 expression was higher in normal than in cancer tissues (p<0.05)." (PMID 33425757, 2020). "DKK3 has been reported to be abnormally expressed in various cancers, contributing to migration and invasion of cancer cells through multiple pathways 28-30." (PMID 32284738, 2020). "For example, atrophies due to starvation and cancer cachexia can occur independently of Dkk-3 activation." (PMID 33023021, 2020). "In agreement, silencing Kremen receptors in Dkk3-null CAFs increased their abilities to remodel gels and promoted cancer cell growth and invasion." (PMID 30631061, 2019). "Since the authentication of target genes is the pivotal step in evaluating the function of miRNAs that are abnormally expressed in cancers, we applied three bioinformatics programs to predict the latent targets of miR-92a, finally focused on DKK3." (PMID 30926679, 2019).
cancer (continued). "Confirming this, expression of a constitutively active mutant of YAP in Dkk3-null CAFs was able to recover their gel remodelling and cancer cell growth promoting abilities." (PMID 30631061, 2019). "DKK3 expression is ubiquitously detected in mouse and normal human tissues, however it is significantly depleted in various cancer cell types." (PMID 31737564, 2019). "DKK3 also activates β-catenin in CAFs and we document that cancer stroma and CAFs present increased β-catenin activity." (PMID 30631061, 2019). "Dickkopf‐3 (DKK3) is frequently down‐regulated by promoter hypermethylation and is closely associated with a poor prognosis in many cancers." (PMID 29673070, 2018). "Comparison of TGFBI and Dkk-3 staining in cancer found high levels of TGFBI in some tumors that expressed low levels of Dkk-3, suggesting an inverse correlation." (PMID 29858602, 2018). "DKK3 expression is frequently silenced in cancer, often by the hyper-methylation of CpG islands located in the Dkk3 locus and ectopic over-expression of DKK3 slows ß-catenin driven cancer cell proliferation in vitro." (PMID 28738084, 2017). "On the other hand, the DNA methylation levels of DKK3 in normal crypts from regions adjacent to the cancer and distal regions on the left side of the colon were significantly higher than those on the right side." (PMID 28533824, 2017). "Reduced expression in immortalized cells/Dickkopf-3 (REIC/Dkk-3) was identified as a gene whose expression is reduced in a variety of human cancer cells." (PMID 28978116, 2017). "In other cancer types, over-expression of DKK3 significantly impaired SW-13 cells’ ability to invade through reconstituted matrix (p < 0.001)." (PMID 28249601, 2017). "For example, DKK3 is downregulated in various types of cancer, such as liver, breast, and prostate, but it is not downregulated in HNSCC cells." (PMID 28708091, 2017). "DKK3 expression is down-regulated in many human cancers, including that of the thyroid, lung, prostate, colon, breast, and liver, but its regulation in ACC is unclear." (PMID 28249601, 2017). "Endogenous Dkk-3 is frequently downregulated in cancers and has been studied as a potential anti-oncogene." (PMID 27827955, 2016). "Overexpression of the REIC/Dkk-3 gene showed a potent selective therapeutic effect on various human cancers by triggering ER stress and the UPR." (PMID 27304053, 2016). "Second, to evaluate the Dkk-3 protein expression levels in various kinds of cancer cell lines, we performed Western blot analysis." (PMID 27827955, 2016). "The potential prognostic impact of DKK3 expression indicates a possible functional involvement of DKK3 in the carcinogenesis of the human breast, especially in that of basal and luminal carcinomas." (PMID 27467270, 2016). "The potential prognostic impact of DKK3 expression indicated a possible functional involvement of DKK3 in the carcinogenesis of the human breast, especially in that of basal and luminal carcinomas." (PMID 27467270, 2016). "Because promoter methylation was a reason for silencing the DKK genes in human cancer, so we further investigated the methylation status of the DKK3 promoters." (PMID 26395974, 2015). "REIC/Dkk-3-sensitive cancer cells, IRE1α (an ER stress sensor), apoptosis signal-regulating kinase 1 (ASK1) and JNK activation by Ad-REIC, subsequently induce the phosphorylation of c-Jun." (PMID 24527065, 2014). "REIC/Dkk-3 protein is a secretory protein and the overexpression of this protein induced by Ad-REIC treatment efficiently leads to ER stress-induced apoptosis in cancer cells." (PMID 24527065, 2014). "The authors identified that the Dkk-3 protein inhibits Wnt/β-catenin signaling in specific mammalian cells and cancer cell lines." (PMID 24527065, 2014). "The overexpression of REIC/Dkk-3 with the Ad-CAG-REIC reagent was previously found to induce apoptosis in a broad range of human cancer cell lines in vitro." (PMID 24398705, 2014).
cancer (continued). "Consistently, the REIC/Dkk-3 expression in cancer specimens is downregulated at the critical transition from low- to high-level malignant disease." (PMID 24527065, 2014). "We previously demonstrated that overexpression of REIC/Dkk-3 using a replication incompetent adenovirus vector (Ad-REIC) specifically induced apoptosis in various cancer cells." (PMID 24526517, 2014). "This implies that, due to the poor capacity for REIC/Dkk-3 gene expression, the cancer cells easily exhibit a failure to fold large amounts of REIC/Dkk-3 protein accumulated in the ER." (PMID 24527065, 2014). "The overexpression of REIC/Dkk-3 induced by the Ad-REIC agent was found to stimulate apoptosis in a broad range of human cancer cell lines in vitro." (PMID 24527065, 2014). "Our results are in line with previous studies of DKK3 down-regulation and methylation in a variety of cancer cell lines and tissues, and its transcriptional silencing is at least partly because of aberrant hypermethylation of the promoter." (PMID 23890219, 2013). "The low expression of DKK3 in several human cancers combined with its cancer specific apoptosis inducing effects suggest that re-establishing DKK3 holds promise as a novel targeted cancer therapy." (PMID 23226679, 2012). "Despite, within the cohort of carcinomas being affected by methylation of either the DKK3 or WIF1 gene, a large fraction (45%) showed methylation in one gene only." (PMID 19570204, 2009). "Expression of the putative Wnt signalling inhibitor Dickkopf-3 (DKK3) is frequently lost in human cancer tissues because of aberrant 5'-cytosine methylation within the DKK3 gene promoter." (PMID 18826564, 2008). "Recently, we developed a complementary peptide targeting DKK3 (DKK3-CP) as a new anticancer substance and reported that DKK3-CP could significantly suppress cancer cell growth, migration, and invasion in OSCC-derived cells." (PMID 40917921, 2025). "The in vitro experiment results showed that DKK3-CP could significantly suppress the cancer cell viability, cellular migration, and cellular invasion." (PMID 40917921, 2025). "Additionally, ectopic expression of DKK3 suppresses malignant invasion and migration and reverses EMT effects in multiple cancer cell types, indicating that DKK3 also has a dedifferentiation-blocking function." (PMID 38269250, 2023). "However, to fully exploit this promise, further investigations are needed to understand the different activities of DKK-3 and to optimize therapeutic strategies that take into account context and cancer-type dependence." (PMID 38201279, 2023). "This suggests that DKK-3 may possibly inhibit cancer proliferation by inhibiting both Wnt and EGFR signaling." (PMID 38201279, 2023). "REIC/Dkk-3 thus has diverse roles in different cell types in different cancer milieus that lead to cancer suppression or cancer progression, or both at the same time depending on the plural in situ contexts, because of the presence of multiple receptors to the extracellular REIC/Dkk-3." (PMID 36869893, 2023). "A problem remains, however: the REIC/Dkk-3 protein promotes cancer in a few cases." (PMID 36869893, 2023). "Our results revealed that extracellular REIC/Dkk-3 protein makes PD-L1 break away from the chemokine receptors that sequester PD-L1 in the cytoplasmic compartment, leading to an accelerated degradation of PD-L1; cancer immune evasion is thereby dampened." (PMID 36869893, 2023). "Our finding that showed high expression of DKK3 in cancer stroma compared to normal adjacent tissue, which is unique to the Middle Eastern patients, might need further elucidation with a higher patient sample size." (PMID 36845147, 2023). "DKK3 expression is downregulated in several types of human cancers." (PMID 36497305, 2022). "Navitoclax reduced the growth of GBM cancer cell lines exhibiting high DKK3 expression." (PMID 35599254, 2022).